AZIN1 (antizyme inhibitor 1)
Description:
Antizyme inhibitor (AZI) protein that positively regulates ornithine decarboxylase (ODC) activity and polyamine uptake. AZI is an enzymatically inactive ODC homolog that counteracts the negative effect of ODC antizymes (AZs) OAZ1, OAZ2 and OAZ3 on ODC activity by competing with ODC for antizyme-binding. Inhibits antizyme-dependent ODC degradation and releases ODC monomers from their inactive complex with antizymes, leading to formation of the catalytically active ODC homodimer and restoring polyamine production.
Synonyms: AZI; AZI1; OAZI; OAZIN; ODC1L; AZIA1
Tractability: Small molecule: it belongs to a druggable protein family. PROTAC: UniProt records ubiquitination sites on it; ubiquitination databases record sites on it.
Gene: Protein-coding gene on chromosome 8 (102,826,111 to 102,893,864, reverse strand). Ensembl gene ENSG00000155096.
Subcellular location: Nucleus
Subcellular location (Human Protein Atlas): Nucleoli; Nucleoli rim
Pathways (Reactome):
Metabolism: Regulation of ornithine decarboxylase (ODC)
Gene Ontology:
Molecular function: ornithine decarboxylase activator activity; protein binding; ornithine decarboxylase activity; catalytic activity
Biological process: negative regulation of protein catabolic process; positive regulation of polyamine transmembrane transport; polyamine biosynthetic process
Cellular component: cytoplasm; nucleus
Genetic constraint (gnomAD): Loss-of-function variants: 6 observed, 32.89 expected, observed/expected ratio (o/e) 0.18, 90% interval 0.099 to 0.36. The upper end of that interval is the gene's LOEUF score, 0.36, which puts it in group 1 of 6, group 1 being the genes least tolerant of losing a copy. Missense variants: 340 observed, 478.91 expected, observed/expected ratio (o/e) 0.71, 90% interval 0.65 to 0.78. Synonymous variants: 136 observed, 162.75 expected, observed/expected ratio (o/e) 0.84, 90% interval 0.73 to 0.96.
Homologues: Orthologues: chimpanzee AZIN1 (100% identical), macaque AZIN1 (99% identical), mouse Azin1 (96% identical), pig AZIN1 (95% identical), rat Azin1 (93% identical), guinea pig AZIN1 (85% identical), tropical clawed frog azin1 (67% identical), rabbit AZIN1 (62% identical), zebrafish azin1b (54% identical), zebrafish azin1a (53% identical), Drosophila melanogaster Odc1 (33% identical), Drosophila melanogaster Odc2 (32% identical), and 1 more. Paralogues in human: ODC1 (51% identical), AZIN2 (43% identical).
Diseases named in the same sentence as AZIN1 in open-access papers:
AZIN1 is named in the same sentence as 56 diseases in open-access papers, as found by Europe PMC text mining. Sharing a sentence is not in itself a finding about the gene and the disease. The quoted sentences say what the papers report.
hepatocellular carcinoma (35 papers, 2014 to 2025). A malignant tumor that arises from hepatocytes. "So far, only editing of one target, Azin1 RNA, was implicated in a pathology, hepatocellular carcinoma." (PMID 30087110, 2018). "Two cancers associated with increased editing on AZIN1 are hepatocellular carcinoma (HCC) and esophageal squamous cell cancer (ESCC)." (PMID 27999332, 2016). "RNA editing deregulation has begun to be linked to cancer, including in hepatocellular carcinoma, where recurrent editing of AZIN1 promotes pathogenesis." (PMID 25036877, 2014). "Notably, site-specific RNA editing of AZIN1 – a regulator of tumor growth – causes exon recoding resulting in enhanced protein stability and is associated with aggressive hepatocellular carcinoma." (PMID 25889244, 2015). "In hepatocellular carcinoma (HCC) increased editing of the transcript encoding antizyme inhibitor 1 (AZIN1) by ADAR1 results in increased cell proliferation." (PMID 26437436, 2015). "Similar results were obtained for hepatocellular carcinoma where the degree of antizyme inhibitor 1 (AZIN1) was related to carcinogenesis, initiation, and development." (PMID 39641903, 2025). "Specifically, one recoding site located in AZIN1 has previously shown to be differentially edited between hepatocellular carcinoma, non-small-cell lung cancers, esophageal squamous cell carcinoma, and colorectal cancer, and their respective normal tissues." (PMID 39062643, 2024). "Many studies suggest that RNA editing at the S/G site of AZIN1 is increased in multiple cancers, such as hepatocellular carcinoma, esophageal squamous cell carcinoma, gastric cancer, and colorectal cancer." (PMID 37209819, 2023). "AZIN1 has been identified as one of the most frequently occurring A-to-I RNA alterations in colorectal cancer and hepatocellular carcinoma and acts as an oncogene." (PMID 37760246, 2023). "Edited AZIN1 promotes tumor cell proliferation, invasion, and migration in a wide range of cancers, including hepatocellular carcinoma, non-small-cell lung cancer, colorectal cancer, and esophageal squamous cell carcinoma." (PMID 37328893, 2023). "First, ADAR1-mediated A-to-I editing of AZIN1 enhanced tumorigenesis in hepatocellular carcinoma and esophageal squamous cell carcinoma." (PMID 35406793, 2022). "Several recent studies show that antizyme inhibitor 1 (AZIN1) is one of the most common A-to-I RNA alterations in various cancer types, including hepatocellular carcinoma, non-small cell lung cancer, colorectal cancer (CRC)." (PMID 35365616, 2022). "In the seminal paper, transcriptomic sequencing of several human hepatocellular carcinomas revealed that adenosine-to-inosine (A→I) RNA editing of AZIN1 was increased in tumors with respect to healthy liver tissue." (PMID 30304856, 2018). "Recently, elevated editing of AZIN1 in hepatocellular carcinoma was reported to be related to tumor stages." (PMID 28009993, 2017). "It was noted that the frequency of AZIN1 RNA editing increases during progression from cirrhosis and primary liver cancer to advanced hepatocellular carcinoma with recurrence and metastasis." (PMID 26930599, 2016). "An increased editing of AZIN1 was identified in hepatocellular carcinoma." (PMID 31815657, 2019). "Remarkably, an edited transcript of AZIN1 was firstly detected in human hepatocellular carcinoma." (PMID 30304856, 2018). "Thus, AZIN1 was found to be present in the cytoplasm of hepatoma tissue culture (HTC) cells during interphase, and together with AZ1, at centrosomes during mitosis." (PMID 30304856, 2018). "In hepatocellular carcinoma, A-to-I editing of the antizyme inhibitor 1 (AZIN1) increases and neutralizes a key inhibitor of the polyamine synthesis pathway, thereby promoting proliferation in vitro and increasing tumor initiation and volume in a mouse xenograft model." (PMID 26440892, 2015).
hepatocellular carcinoma (continued). "In hepatocellular carcinoma (HCC), A-to-I RNA editing of AZIN1 promotes tumorigenesis by stabilizing pro-proliferative proteins like ODC and cyclin D1, which bind more strongly to antizyme." (PMID 41361128, 2025). "For instance, in human hepatocellular carcinoma (HCC), there is an increased frequency of AZIN1 editing at residue 367 (Ser to Gly), leading to inhibition of antizyme tumor-suppressor function and contributing to cancer initiation and progression." (PMID 40175891, 2025). "AZIN1 was first found in hepatocellular carcinoma (HCC), and later in colorectal cancer." (PMID 34638933, 2021). "In hepatocellular carcinoma, increased levels of ADAR lead to editing of Antizyme Inhibitor 1 (AZIN1) and consequently enhanced nuclear import of the edited protein and stabilized interaction with its binding partner (Antizyme)." (PMID 33669629, 2021). "In hepatocellular carcinoma (HCC), ADAR1-induced amino acid substitution in antizyme inhibitor 1 (AZIN1) enhances its activity and promotes tumor initiation and development." (PMID 32754274, 2020). "In addition, ADAR1-mediated hyperediting antizyme inhibitor 1 (AZIN1), which is capable of influencing self-renewal and differentiation at the stem cell level, has been discovered in hepatocellular carcinoma (HCC) and colorectal and gastric cancers." (PMID 37280687, 2023). "In hepatocellular carcinoma (HCC), esophageal squamous cell carcinoma (ESCC), colorectal cancer (CRC) and breast cancer (BC), overexpression of ADAR1 leads to the creation of an oncogenic version of antizyme inhibitor 1 (AZIN1; S367G)." (PMID 30619092, 2018).
colorectal cancer (20 papers, 2016 to 2025). A primary or metastatic malignant neoplasm that affects the colon or rectum. "Activation of AZIN1 RNA editing by ADAR1 facilitates invasive capacity of cancer-associated fibroblasts in colorectal carcinoma." (PMID 38468359, 2024). "ADAR1-driven activation of AZIN1 RNA editing has been reported to promote the invasive potential of cancer-associated fibroblasts in colorectal cancer (CRC)." (PMID 33750389, 2021). "In colorectal cancer, adenosine-to-inosine (A-to-I) RNA editing of antizyme inhibitor 1 (AZIN1) by ADAR1 has been shown to increase CAF invasiveness, highlighting the importance of RNA editing in modulating CAF functions." (PMID 40176140, 2025). "RNA-edited AZIN1 enhances colorectal cancer (CRC) stemness and appears to drive the metastatic processes." (PMID 38169396, 2024). "Other studies demonstrated that edited AZIN1 confers the invasive potential of CAFs in colon cancer and predicts tumor invasiveness in colorectal cancer." (PMID 38169396, 2024). "In liver cancer, editing of the antizyme inhibitor AZIN1 induces its cytoplasmic-to-nuclear translocation to increase tumor aggressiveness, whereas in colorectal cancer, ATIRE impacts Ras homolog family member Q (RHOQ) to promote invasion." (PMID 36999050, 2023). "Elevated expression of ADAR1 level and AZIN1 RNA modification is observed in colorectal cancer tissues from patients compared to normal colon epithelial cells." (PMID 32194861, 2020). "Antizyme inhibitor 1 (AZIN1) is found to be one of the most frequently modified genes in colorectal cancer (CRC)." (PMID 32194861, 2020). "Interestingly, a growing number of studies reported that AZIN1 expression increased in most cancer types, including gastric cancer, ovarian cancer and prostate cancer and colorectal cancer." (PMID 38169396, 2024). "We extracted the conditioned media (CM) from colorectal cancer cells for co-culture with HUVEC to explore whether enhanced RNA editing of AZIN1 from cancer cells can influence tumor angiogenesis." (PMID 35365616, 2022). "In addition, edited AZIN1 promotes cancer invasion, migration, and stemness in colorectal cancers." (PMID 37209819, 2023). "To date, overexpression of ADAR1 and increased AZIN1 RNA editing in cancer tissues has been demonstrated in various other types of cancers, including HCC, non-small-cell lung, esophageal, and colorectal cancer." (PMID 30563560, 2018). "Interestingly, several functional A-to-I events have been reported in cancer, such as AZIN1 editing in liver and colorectal cancer and RHOQ editing in colorectal cancer." (PMID 36969056, 2023). "The results of coexpression analysis coupled to ENCODE ChIP-Seq data strongly suggest c-Myc and C/EBPβ as regulators of the expression of key enzymes of polyamine metabolism that are upregulated in colorectal cancer: SMOX, AZIN1, MTAP, SRM, AMD1, ODC1, and AGMAT." (PMID 27433286, 2016).
gastric cancer (10 papers, 2018 to 2025). A primary or metastatic malignant neoplasm involving the stomach. "Since two pioneering reports introduced the impact of ADAR1 on gastric cancer progression, others have reported targets including antizyme inhibitor 1 (AZIN1), the mTOR/p70S6K pathway, and phosphatase and actin regulator 4 (PHACTR4)." (PMID 39825637, 2025). "AZIN1 RNA-editing level in primary tumor tissues is significantly correlated with lymph node metastasis in gastric cancer patients." (PMID 38169396, 2024). "Since two pioneering reports introduced the impact of ADAR1 in gastric cancer progression, others have reported targets including Antizyme Inhibitor 1 (AZIN1), mTOR/p70S6K pathway, and Phosphatase And Actin Regulator 4 (PHACTR4)." (PMID 32867271, 2020). "Among the fourteen A-to-I non-synonymous editing events, three ones have been experimentally dissected as pivotal modulators involving in tumorigenesis, including A1099G at AZIN1 in HCC, A725G at NEIL1 in glioblastoma and A722G at PODXL in gastric cancer." (PMID 36476255, 2022).
esophageal squamous cell carcinoma (9 papers, 2018 to 2025). Esophageal squamous cell carcinoma (ESCC) is a type of esophageal carcinoma (EC) that can affect any part of the esophagus, but is usually located in the upper or middle third. "Over-editing of AZIN1 has also been implicated in other cancers, such as esophageal squamous cell carcinoma." (PMID 30197877, 2018). "In addition to hepatocellular carcinoma, AZIN1 RNA editing levels are also significantly elevated in esophageal squamous cell carcinoma (ESCC), non-small-cell lung cancer and colorectal cancer when compared with corresponding normal mucosa." (PMID 30585209, 2018). "Oncogenic recoding site S to G in AZIN1, which participates in cancer growth, invasion, and migration, was detected in various cancers, such as liver hepatocellular carcinoma (LIHC), esophageal squamous cell carcinoma (ESCC), non-small cell lung cancer (NSCLC), and colorectal cancer (CRC)." (PMID 38203521, 2023).
breast carcinoma (6 papers, 2014 to 2024). "This study reveals the metabolic pathways involved in estrogen-mediated monocarbon, purine and polyamine synthesis in breast cancer, and the discovery that PPAT and AZIN1 were direct ERa targets for the cell survival and growth of breast cancer." (PMID 31391919, 2019). "For Breast cancer 6 genes had significant aCGH/expression correlation at a level of 0.05 in all 7 breast cancer data sets (BCL9, AZIN1, TAF2, YTHDF1, TTC13, FBXL20)." (PMID 25148247, 2014).
renal fibrosis (6 papers, 2015 to 2024). A final common manifestation of a wide variety of chronic kidney diseases characterized by glomerulosclerosis and tubulointerstitial fibrosis. "In this context, increased Azin1 expression has been also correlated with the amelioration of renal fibrosis associated to diabetic nephropathy." (PMID 30304856, 2018). "Antizyme inhibitor 1 has also been implicated in the regulation of renal fibrosis, since AZIN1 overexpression suppressed transforming growth factor β (TGF-β)/Smad3 signalling pathway, a major player in tissue fibrosis." (PMID 30304856, 2018). "The regulation of AZIN1, at least in the context of renal fibrosis is mediated by the miR-433, as the authors demonstrated that overexpression of miR-433 suppressed Azin1 expression." (PMID 38918813, 2024). "Previous studies revealed that miR-433 plays a regulatory role in tissue fibrosis, it promotes renal fibrosis by targeting AZIN1 to activate the TGF-β/SMAD3 signaling pathway." (PMID 35255830, 2022). "In addition, polyamine depletion activates TGF-βsignaling and our laboratory recently demonstrated that depletion of cellular polyamine levels by targeting Azin1 with a Smad3-dependent miR-433 exaggerates TGF-β-induced renal fibrosis." (PMID 25750628, 2015). "As Azin1 promotes polyamine synthesis and polyamine depletion can activate TGF-β signaling by increasing the expression levels of TGF-β1, TβRI, and Smad3, elevation of miR-433 during renal fibrosis forms a positive feedback loop to amplify TGF-β signaling by suppressing Azin1 expression." (PMID 25750628, 2015). "For instance, studies have demonstrated that TGF-β/Smad3 promotes renal fibrosis by inducing the expression of miR-21, miR-433, and miR-192, which in turn suppressed PTEN, Smad7, ZEB1/2, and AZIN1, respectively." (PMID 32587662, 2020).
liver cancer (4 papers, 2020 to 2024). An epithelial or non-epithelial malignant neoplasm that arises from the liver. "As is illustrated in liver cancer, A-to-I RNA editing of AZIN1 may facilitate tumorigenesis through neutralizing antizyme mediated degradation of ODC and cyclin D. Furthermore, the nuclear translocation of RNA-edited AZIN1 is required for increased tumor aggressiveness." (PMID 38169396, 2024). "Compared to wild-type AZIN1, edited AZIN1-S367G has stronger antizyme binding and inhibits antizyme-mediated degradation of ODC and cyclin D1, thereby facilitating entry into the cell cycle and increasing the malignancy of liver cancer cells." (PMID 32346127, 2020).